NEDD1 (NEDD1 gamma-tubulin ring complex targeting factor)
Description:
Required for mitosis progression. Promotes the nucleation of microtubules from the spindle.
Synonyms: GCP-WD; TUBGCP7
Tractability: PROTAC: ubiquitination databases record sites on it; its protein half-life has been measured.
Gene: Protein-coding gene on chromosome 12 (96,907,224 to 96,953,780, forward strand). Ensembl gene ENSG00000139350.
Subcellular location: Cytoplasm, cytoskeleton, microtubule organizing center, centrosome
Subcellular location (Human Protein Atlas): Centrosome; Nucleoplasm
Pathways (Reactome):
Cell Cycle: AURKA Activation by TPX2; Loss of Nlp from mitotic centrosomes; Loss of proteins required for interphase microtubule organization from the centrosome; Recruitment of NuMA to mitotic centrosomes; Recruitment of mitotic centrosome proteins and complexes; Regulation of PLK1 Activity at G2/M Transition
Organelle biogenesis and maintenance: Anchoring of the basal body to the plasma membrane
Gene Ontology:
Molecular function: protein binding; gamma-tubulin binding
Biological process: microtubule nucleation; mitotic cell cycle
Cellular component: centrosome; centriole; ciliary basal body; cytoplasm; cytosol; spindle pole; apical part of cell; pericentriolar material
Genetic constraint (gnomAD): Loss-of-function variants: 9 observed, 18.65 expected, observed/expected ratio (o/e) 0.48, 90% interval 0.29 to 0.84. The upper end of that interval is the gene's LOEUF score, 0.84, which puts it in group 3 of 6, group 1 being the genes least tolerant of losing a copy. Missense variants: 262 observed, 284.02 expected, observed/expected ratio (o/e) 0.92, 90% interval 0.83 to 1.02. Synonymous variants: 95 observed, 99.31 expected, observed/expected ratio (o/e) 0.96, 90% interval 0.81 to 1.13.
Homologues: Orthologues: chimpanzee NEDD1 (99% identical), macaque NEDD1 (98% identical), rabbit NEDD1 (91% identical), dog NEDD1 (90% identical), guinea pig NEDD1 (86% identical), rat Nedd1 (86% identical), mouse Nedd1 (85% identical), pig NEDD1 (85% identical). Paralogues in human: MAPKBP1 (19% identical), WDR62 (18% identical), WDR7 (15% identical), TEP1 (13% identical), WDR81 (11% identical), WDR17 (10% identical), WDR75 (9% identical), WDR88 (9% identical), AHI1 (8% identical), POC1B (8% identical), PAFAH1B1 (8% identical), WDR27 (8% identical), and 14 more.
Diseases named in the same sentence as NEDD1 in open-access papers:
NEDD1 is named in the same sentence as 19 diseases in open-access papers, as found by Europe PMC text mining. Sharing a sentence is not in itself a finding about the gene and the disease. The quoted sentences say what the papers report.
lung adenocarcinoma (3 papers, 2022 to 2024). A carcinoma that arises from the lung and is characterized by the presence of malignant glandular epithelial cells. "Based on TCGA database, we found that NEDD1 was highly expressed in various cancer types such as cervical cancer, lung adenocarcinoma, lung squamous cell carcinoma, etc.." (PMID 38577589, 2024). "However, the specific mechanism by which NEDD1 contributes to the progression of lung adenocarcinoma (LUAD) remains unexplored." (PMID 38577589, 2024). "However, the precise role of NEDD1 in the tumor microenvironment of lung adenocarcinoma (LUAD) remains unknown." (PMID 38577589, 2024).
lung carcinoma (2 papers, 2024). "To determine the biological roles of NEDD1 in lung carcinogenesis, we detected the proliferation and metastasis of lung cancer cells using gain-of-function or loss-of-function assays." (PMID 39247593, 2024). "Cytobehavioral experiments targeting NEDD1 through knockdown approaches have also confirmed its promotion of proliferation, migration, invasion, and epithelial-mesenchymal transition in lung cancer cells." (PMID 38577589, 2024). "The most prevailing types of lung cancer are adenocarcinoma and squamous cell carcinoma; when analyzing the TCGA database, we found that the mRNA expression of NEDD1 in LUAD tissues was much higher than that in regular lung tissue from the same individual." (PMID 39247593, 2024). "NEDD1 serves as a dependable prognostic marker for LUAD, as it elevates the risk of developing this type of lung cancer through synergistic interactions with various cancer susceptibility genes." (PMID 38577589, 2024). "Our study discovered that NEDD1 displays abnormal upregulation in various types of solid tumors, including breast, liver, colon, esophageal, and lung cancers." (PMID 38577589, 2024). "In the current study, we investigated the expression of NEDD1 in lung cancer, analyzed the relationship between clinicopathological characteristics and NEDD1 expression at mRNA and protein levels, and explored the role of NEDD1 in lung carcinogenesis." (PMID 39247593, 2024). "We found that NEDD1 knockdown inhibits lung cancer cells proliferation, migration, EMT, and tumor formation in vivo." (PMID 39247593, 2024). "Because gene dysfunction is always accompanied by abnormal expression, it is vital to detect the expression level of NEDD1 in clinical lung carcinoma samples." (PMID 39247593, 2024). "For instance, the kinesin Eg5, which interacts with NEDD1 29, has a similar subcellular location as NEDD1 and is overexpressed in several solid tumors, including lung cancer 30, 31, which leads to genomic instability and promotes cancer progression." (PMID 39247593, 2024). "Moreover, as shown by Kaplan-Meier survival curves, lung cancer patients with high NEDD1 expression had significantly poor prognoses than those with low NEDD1 expression." (PMID 39247593, 2024). "In addition, we explored the impact of NEDD1 on the treatment of CAR-T for lung cancer." (PMID 38577589, 2024). "In addition, the expression of NEDD1 in LUAD was verified by qPCR and IHC, then siRNA was used to construct NEDD1-knocked lung cancer cells for subsequent cytobehavioral experiments." (PMID 38577589, 2024). "In summary, our results suggest that NEDD1 plays a vital role in the development of LUAD and may be a potential prognostic marker and promising therapeutic target for lung cancer therapy." (PMID 39247593, 2024). "Moreover, even though knockdown of NEDD1 using RNAi was reported to prolong the survival of scirrhous gastric cancer model mice 17, the role of NEDD1 in lung cancer development is not clear." (PMID 39247593, 2024).
colon carcinoma (1 paper, 2009).
Friedreich ataxia (1 paper, 2024). An inherited condition that affects the nervous system and causes movement problems. "For instance, Nedd1, a gene involved in cellular senescence, exhibited significant downregulation in multiple tissues in FRDAkd mice, reinforcing the vital role Tug1 may play in the cellular biology disrupted in Friedreich's ataxia." (PMID 38846537, 2024).
idiopathic pulmonary fibrosis (1 paper, 2024). Idiopathic pulmonary fibrosis (IPF) is a nonneoplastic pulmonary disease that is characterized by the formation of scar tissue within the lungs in the absence of any known cause. "NEDD1 is mainly expressed in idiopathic pulmonary fibrosis cells, cancer stem cells, brush cells, lung epithelial cells, secretory cells, and mesenchymal stromal cells." (PMID 38577589, 2024).
cancer (6 papers, 2009 to 2025). A tumor composed of atypical neoplastic, often pleomorphic cells that invade other tissues. "To further explore the additional cancer-promoting effects of NEDD1, we performed differential analysis, PPI network interaction and functional enrichment analysis according to the expression of NEDD1." (PMID 38577589, 2024). "To assess the importance of NEDD1 for cancer cell growth, we tested a variety of cell lines for NEDD1 expression by immunoblotting." (PMID 19243593, 2009). "Furthermore, the effect of NEDD1 on cancer cell proliferation in vivo was investigated in nude mice." (PMID 39247593, 2024). "Whether NEDD1 is indeed a potential target for cancer therapy remains to be determined in animal models in vivo." (PMID 19243593, 2009). "HER2-enriched cancers involved four regulators of PLK1 activity at G2/M transition in the cell cycle, CEP63, CEP250, NEDD1, and HAUS3." (PMID 40700427, 2025). "Ingenuity pathway analysis revealed that differentially methylated CpG sites were annotated to genes involved in ‘cell cycling’ (e.g. NDRG1, NEDD1, and MAD1L1), ‘inflammatory diseases’ (e.g. PRTN3), and ‘cancer’ (PCDHA6, MUC4, and ATP2C2)." (PMID 28754985, 2017). "We show here that NEDD1 expression is not deregulated in cancer cells: NEDD1 is expressed at comparable levels in a variety of cancer cell lines and in normal cells." (PMID 19243593, 2009). "Consequently, NEDD1 could serve as a promising new therapeutic target for LUAD, providing an emerging treatment avenue by directly inducing cancer cell death or increasing the sensitivity of LUAD to immune checkpoint inhibitors and CAR-T cell therapies." (PMID 38577589, 2024).
tumor (3 papers, 2009 to 2024). "We believe that revealing the cause of NEDD1 overexpression in tumor tissue is of great significance for understanding tumor occurrence." (PMID 39247593, 2024). "Furthermore, NEDD1-mediated chromosomal instability can contribute to an increased risk of immune evasion and resistance to frontline chemotherapy drugs and immunotherapeutic agents in tumor cells." (PMID 38577589, 2024). "Based on the functional characteristics of NEDD1 in LUAD and the effect on tumor-infiltrating immune cells, we further analyzed the relationship between NEDD1 expression and drug resistance in chemotherapy and targeted therapy drugs." (PMID 38577589, 2024). "The ssGSEA analysis showed that the positive correlation with NEDD1 expression was mainly immunosuppressive cells, while the main anti-tumor immune cells were negatively correlated." (PMID 38577589, 2024). "Results of tumor volume and tumor weight analysis shown that tumor growth in NEDD1-overexpressing group was promoted (p = 0.002); on the contrary, the growth of tumor in vivo was significantly suppressed in NEDD1- deficient groups (p = 0.004)." (PMID 39247593, 2024). "We show that NEDD1 is expressed at comparable levels in a variety of tumor-derived cell lines and untransformed cells." (PMID 19243593, 2009). "At the same time, the expression of NEDD1 in LUAD increases, which increases the infiltration of a variety of immunosuppressive cells and decreases the infiltration of major anti-tumor immune cells." (PMID 38577589, 2024).
adenocarcinoma (1 paper, 2024). A common cancer characterized by the presence of malignant glandular cells. "To identify NEDD1 overexpression at the protein level, we used immunohistochemistry to detect NEDD1 in a LUAD tissue array comprising 98 cases and found a similar significant difference between adenocarcinoma tissues and normal lung tissues (p = 0.010)." (PMID 39247593, 2024).
NEDD1 also shares sentences with these, for which no sentence is quoted: neuroblastoma (2 papers); bladder cancer (1); cervical cancer (1); colorectal adenocarcinoma (1); gastric cancer (1); lung squamous cell carcinoma (1); maturity onset diabetes (1); non-small cell lung carcinoma (1); Obesity (1); squamous cell carcinoma (1); viral infection (1).